WNT6 (Wnt family member 6)
Description:
Ligand for members of the frizzled family of seven transmembrane receptors. Probable developmental protein. May be a signaling molecule which affects the development of discrete regions of tissues. Is likely to signal over only few cell diameters. Together with CAV1 may promote chemoresistance of gastric cancer cells to DNA-damaging anthracycline drugs through the activation of the canonical Wnt receptor signaling pathway.
Tractability: Antibody: its Gene Ontology location is reachable by antibodies, with high confidence; UniProt places it where antibodies can reach, with medium confidence; UniProt predicts a signal peptide or a membrane-spanning region.
Gene: Protein-coding gene on chromosome 2 (218,859,805 to 218,874,233, forward strand). Ensembl gene ENSG00000115596.
Subcellular location: Secreted, extracellular space, extracellular matrix
Pathways (Reactome):
Signal Transduction: Class B/2 (Secretin family receptors); WNT ligand biogenesis and trafficking
Gene Ontology:
Molecular function: cytokine activity; frizzled binding; signaling receptor binding
Biological process: odontogenesis of dentin-containing tooth; positive regulation of gene expression; positive regulation of tooth mineralization; canonical Wnt signaling pathway; cell fate commitment; cellular response to retinoic acid; cornea development in camera-type eye; neuron differentiation; Wnt signaling pathway
Cellular component: endocytic vesicle membrane; endoplasmic reticulum lumen; extracellular exosome; extracellular region; Golgi lumen; plasma membrane; cell surface; extracellular matrix
Genetic constraint (gnomAD): Loss-of-function variants: 27 observed, 21.81 expected, observed/expected ratio (o/e) 1.24, 90% interval 0.91 to 1.7. The synonymous counts are far from expectation, so gnomAD's model fits this gene poorly and the ratio says little. Missense variants: 494 observed, 435.55 expected, observed/expected ratio (o/e) 1.13, 90% interval 1.05 to 1.22. Synonymous variants: 249 observed, 184.63 expected, observed/expected ratio (o/e) 1.35, 90% interval 1.22 to 1.5.
Homologues: Orthologues: chimpanzee WNT6 (99% identical), macaque WNT6 (99% identical), dog WNT6 (98% identical), rat Wnt6 (98% identical), mouse Wnt6 (98% identical), guinea pig WNT6 (97% identical), pig WNT6 (97% identical), rabbit WNT6 (91% identical), zebrafish wnt6b (69% identical), tropical clawed frog wnt6 (63% identical), Drosophila melanogaster Wnt6 (45% identical). Paralogues in human: WNT1 (44% identical), WNT10B (42% identical), WNT4 (42% identical), WNT10A (40% identical), WNT3 (40% identical), WNT3A (40% identical), WNT5A (39% identical), WNT5B (39% identical), WNT2B (38% identical), WNT7B (38% identical), WNT2 (38% identical), WNT7A (37% identical), and 6 more.
Diseases named in the same sentence as WNT6 in open-access papers:
WNT6 is named in the same sentence as 56 diseases in open-access papers, as found by Europe PMC text mining. Sharing a sentence is not in itself a finding about the gene and the disease. The quoted sentences say what the papers report.
bladder cancer (13 papers, 2015 to 2023). "Urothelial cancer-associated 1 (UCA1) has been found to be overexpressed in bladder cancer cell lines and induce less apoptosis after DDP treatment, partially through activating the wingless-type MMTV integration site family member 6 (Wnt6) signaling pathway." (PMID 32122355, 2020). "The increased level of lncRNA UCA1 activated Wnt signaling and resulted in the cisplatin resistance of bladder cancer cells in a Wnt6-dependent manner." (PMID 31143372, 2019). "Fan reported that UCA1 plays an important role in the chemoresistance of bladder cancer by activating Wnt signaling in a Wnt6-dependent manner." (PMID 28209917, 2017). "LncRNA-UCA1 increases cisplatin resistance during bladder cancer chemotherapy by increasing the expression of Wnt6 and thus represents a potential target to overcome bladder cancer chemoresistance." (PMID 27034004, 2016). "CUDR increases the cisplatin resistance of bladder cancer cells by enhancing the expression of Wnt6, and thus represents a potential target to overcome chemoresistance in bladder cancer." (PMID 26513297, 2015). "The lncRNA UCA1 increased Wnt6 expression and cisplatin resistance in bladder cancer cells." (PMID 37405480, 2023). "Similarly, UCA1 increases the cisplatin resistance of bladder cancer cells by enhancing Wnt6 expression, and thus represents a potential target to overcome chemoresistance in bladder cancer." (PMID 33565716, 2021). "Moreover, UCA1 increases cisplatin resistance by upregulating Wnt6 expression and suppressing cell apoptosis in bladder cancer." (PMID 31777598, 2019). "Thus, the UCA1/Wnt6 pathway represents a potential target for conquering chemoresistance in bladder cancer." (PMID 27713133, 2017). "Furthermore, UCA1 remarkably increased expression of Wnt6 in human bladder cancer cell lines, and their expression was also positively correlated in vivo." (PMID 27713133, 2017). "Finally, UCA1 promoted cisplatin resistance of bladder cancer cells by enhancing the expression of Wnt6 and activating Wnt signaling." (PMID 27713133, 2017). "Thus, UCA1/Wnt6 pathway was a potential target for bladder cancer resistance." (PMID 32759948, 2020). "Hence, the UCA1/Wnt6 pathway may be able to prevent bladder cancer." (PMID 37405480, 2023). "Higher lncRNA UCA1 levels were observed in blood samples of advanced bladder cancer patients after cisplatin-based chemotherapy with a positive correlation between UCA1 and Wnt6 mRNA expression levels in the bladder cancer tissues." (PMID 28969100, 2017).
breast carcinoma (8 papers, 2006 to 2022). "MiR-566 represents an important link in this process by targeting WNT6 and preventing malignant progression in breast cancer patients." (PMID 34769207, 2021). "WNT6 was also proved to be a target of miR-566 in human breast cancer." (PMID 34769207, 2021). "Our present study is an extension of our previous work, in which we proposed the co-regulated expression pattern of the WNT gene cluster (WNT-1, WNT-6, WNT-10A and WNT-10B) in human breast carcinoma." (PMID 23372744, 2013). "The Wnts that are likely to be involved in mammary specification and early morphogenesis, such as Wnt3a, Wnt6, and Wnt10b, are also genetically altered in MMTV-induced mammary tumours." (PMID 16933995, 2006). "In breast cancer cells, there is overexpression of WNT3A, WNT4, WNT6, WNT8B, WNT9A and WNT10B." (PMID 35453754, 2022). "WNT3A, WNT4, WNT6, WNT8B, WNT9A, and WNT10B all are overexpressed in many breast cancer cell lines." (PMID 16933995, 2006). "Most importantly, 5 genes were found to be associated with all of the most highly enriched GO terms and KEGG pathways: WNT5A, WNT6, WNT11, WNT5B and LAMA1, which suggested that WNTs may be essential targets of ATBF1 and may contribute to breast cancer tumorigenesis." (PMID 36476423, 2022). "Other breast cancer cells reacted with the induction of different non-canonical WNT ligands, such as WNT5A in SK-BR-3 or WNT6 in T-47D cells." (PMID 34911552, 2021).
gastric cancer (7 papers, 2013 to 2023). A primary or metastatic malignant neoplasm involving the stomach. "In clinical specimens of gastric cancer, the expression of WNT6 positively correlated with the tumor stage and the nodal status and was negatively associated to the response to chemotherapeutic drugs including epirubicin, cisplatin, and 5-fluorouracil." (PMID 35158857, 2022). "Collectively, these findings indicated that resistance to chemotherapeutic drugs in gastric cancer is mediated through upregulated expression of WNT6 and CAV1." (PMID 35158857, 2022). "Yuan's group found that epirubicin increased the activity of the human Wnt6 promoter through Cav1-dependent binding of β-catenin to the proximal Wnt6 promoter in gastric cancer, which is considered an important regulator of CSCs." (PMID 26431273, 2015). "Based on studies in human gastric cancer (GC) cells, WNT6 was able to increase resistance to apoptotic cell death induced by chemotherapeutic agents and enhance resistance of GC cells to anthracycline drugs." (PMID 23505429, 2013). "Furthermore, WNT6 expression in gastric cancer tissues was negatively correlated with response to chemotherapy." (PMID 36982422, 2023). "In addition, Cav-1 also targeted WNT6, an activator of Wnt pathway, to induce chemoresistance to epirubicin in human gastric cancer cells." (PMID 34168559, 2021).
colorectal cancer (5 papers, 2018 to 2023). A primary or metastatic malignant neoplasm that affects the colon or rectum. "The only other known tumor entity characterized by WNT6/WNT10A overexpression are colorectal carcinomas and it is assumed that their mode of proliferation is linked to differential beta-catenin expression—as opposed to PTSMTs." (PMID 29881541, 2018). "For instance, epigenetic inactivation of SERP genes allowed constitutive Wnt signaling pathway in colorectal cancer, while overexpression of Wnt genes (Wnt 3, Wnt5b, Wnt6, Wnt10a, Wnt14, and Wnt16) activated Wnt signaling pathway in Chronic lymphocytic leukemia." (PMID 32904598, 2020). "It was previously shown that WNT6 expression is positively regulated by CAV1 (a scaffolding protein), UCA1 (a long noncoding RNA), and PLAGL2 (a zinc finger protein) in gastric, bladder, and colorectal cancer, respectively." (PMID 31923345, 2020).
glioblastoma (5 papers, 2019 to 2025). The most malignant astrocytic tumor (WHO grade IV). "This indicates that WNT6 promotes the expression of glioblastoma stem cell-associated genes and functionally impacts the self-renewal capacity of the tumor." (PMID 33425886, 2020). "In our study on A172 glioblastoma cells, TQ regulated the expression of key components and regulators of the Wnt signaling pathway by increasing Wnt7B expression(2.2-fold) and decreasing WNT6 expression (1.6-fold)." (PMID 39874307, 2025). "WNT6 was recently identified as a new oncogenic molecule in glioblastoma (GBM), with prognostic value in patients, but the mechanisms underlying WNT6 aberrant expression in glioma are still unknown." (PMID 31923345, 2020). "The concomitant expression of HOXA9 and WNT6 results in overactivation of the WNT/β‐catenin signaling pathway in vitro and in vivo, and identifies a subgroup of glioblastoma patients with particularly dismal prognosis, suggesting this HOXA9‐WNT6 link may be an attractive therapeutic target." (PMID 31923345, 2020).
glioma (4 papers, 2020 to 2025). A benign or malignant brain and spinal cord tumor that arises from glial cells (astrocytes, oligodendrocytes, ependymal cells). "Together, these results show that high WNT6 expression associates with higher glioma grades independently of IDH mutation and 1p/19q codeletion status." (PMID 31923345, 2020). "WNT6 was overexpressed in a subset of gliomas independently of IDH mutations, 1p/19q codeletion status, and WNT6 gene copy number." (PMID 31923345, 2020). "In contrast, our findings demonstrated that DNA methylation, a critical epigenetic mechanism, associates with WNT6 expression levels in glioma, similarly to what was observed for other WNT ligands in other cancer types." (PMID 31923345, 2020). "In glioma, the DNA methylation level of the WNT6 promoter and specific CpG regions on the genome is associated with the expression level of WNT6." (PMID 33425886, 2020). "To reach our goal of understanding the mechanisms underlying WNT6 activation in glioma, we integrated data from (epi)genetic and in silico analyses from patients and cell lines." (PMID 31923345, 2020). "Our data showed that WNT6‐high expression in glioma increases with grade independently of IDH mutation and 1p/19q codeletion status." (PMID 31923345, 2020). "We next evaluated WNT6’s DNA methylation levels in glioma patients and investigated whether these might be associated with WNT6 expression levels." (PMID 31923345, 2020). "Notwithstanding, further studies are warranted, as other transcription factors, as well as other regulatory mechanisms, might also be implicated in the regulation of WNT6 in glioma." (PMID 31923345, 2020). "Interestingly, WNT6 expression is associated with the DNA methylation levels of particular CpG regions at both the WNT6 promoter and the gene body in glioma patient samples." (PMID 31923345, 2020). "By integrating in vitro and in vivo models, and data from patients, this study unravels a novel molecular link between the homeobox HOXA9 gene and WNT6 in glioma, which has prognostic relevance in patients with highly aggressive GBMs." (PMID 31923345, 2020). "Notwithstanding, other potential transcriptional regulatory mechanisms, such as WNT6 promoter‐binding transcription factors, are likely to be involved in WNT6 activation in glioma." (PMID 31923345, 2020). "Together, these results suggest that WNT6 DNA methylation levels contribute, at least partially, to regulate WNT6 expression in glioma." (PMID 31923345, 2020). "In various cohorts of glioma patients, mRNA levels of WNT6 and HOXA9 were significantly correlated, extending our in vitro and in vivo findings into the clinical setting." (PMID 31923345, 2020). "To understand the mechanisms responsible for WNT6 overexpression in glioma, we started by investigating copy number alterations of the WNT6 locus in LGG (n = 509) and GBM (n = 565) patients from TCGA." (PMID 31923345, 2020). "This indicates that WNT6 DNA methylation is at least partly involved in the regulation of WNT6 expression in gliomas." (PMID 33425886, 2020). "Analysis of TCGA and other dataset of glioma tissues has shown that certain GBM patients show high expression of wnt6 mRNA and protein in tumor cells." (PMID 33425886, 2020). "Although DNA methylation was clearly associated with WNT6 expression in glioma, this association was not universal." (PMID 31923345, 2020). "First, we observed that WNT6 is expressed in a gene dosage‐independent manner in glioma." (PMID 31923345, 2020). "Varied expression levels of Wnt pathway components in gliomas have been observed, such as elevated WNT3A and 5A and decreased WNT7B, and the oncogenic role of overexpressed WNT6." (PMID 39874307, 2025). "Analysis of The Cancer Genome Atlas (TCGA) has shown that in low-grade glioma, wnt6 mRNA is not overexpressed." (PMID 33425886, 2020).
glioma (continued). "Interestingly, it was recently reported that HOXA genes are part of a gene‐signature characteristic of WNT‐dependent glioma stem cells, which fits well with our data linking HOXA9 and WNT6 in GBM." (PMID 31923345, 2020). "Moreover, WNT6 and HOXA9 were not only co‐expressed in glioma, but also in leukemia, a cancer type where the oncogenic roles of HOXA9 are well established, and also in TGCT, CHOL, and melanoma." (PMID 31923345, 2020). "Interestingly, this novel molecular link between WNT6 and HOXA9 was not limited to glioma, as they were co‐expressed also in patients with other tumor types." (PMID 31923345, 2020). "However, while these genes have been described to be expressed in glioma, we found the transcriptional levels of WNT6 are not significantly correlated with CAV1 (r = −0.03, P = 0.66) or PLAGL2 (r = 0.07, P = 0.36) in human GBM, and UCA1 and WNT6 are inversely correlated (r = −0.29, P < 0.001)." (PMID 31923345, 2020).
melanoma (4 papers, 2020 to 2024). A malignant, usually aggressive tumor composed of atypical, neoplastic melanocytes. "Transfection of melanoma cell lines with a pool of siRNAs against Wnt6 led to a reduction in Wnt6 mRNA expression of ~40% after 48 h." (PMID 38388496, 2024). "Incubation with just one Wnt ligand, either Wnt6 or Wnt10b, led to a disruption in the OIS of BRAFm-transduced melanocytes from OIS, whereas in melanoma cells, knockdown of the respective Wnt6 expression induced a senescent phenotype." (PMID 38388496, 2024). "As we were able to show that Wnts play a role in breaking OIS, we focused on Wnt6, as it was upregulated the most in the tested melanoma cells compared to the NHEMs in OIS." (PMID 38388496, 2024). "It has been shown that these two phenotypes of melanoma are controlled by two distinct Wnt6 pathways." (PMID 38712152, 2024). "Furthermore, depletion of Wnt6, Wnt10b or β-catenin expression in melanoma cells resulted in the induction of senescence." (PMID 38388496, 2024). "Based on the effects of Wnt6 on OIS in melanocytes, we investigated the function of Wnt6 in melanoma cells and determined the status of senescence after the knockdown of Wnt6." (PMID 38388496, 2024). "Although we previously showed that Wnt6 reduces OIS in melanocytes but induces senescence in melanoma cell lines, we wanted to determine whether Wnt10b, which is also upregulated in melanoma cell lines, has a similar function." (PMID 38388496, 2024). "No data are available on Wnt6 in melanoma, but in other tumor types, Wnt6 has been described to act as an oncogene." (PMID 38388496, 2024). "Furthermore, both WNT6 and HOXA9 are co-expressed in GBM and other diseases including leukemia, testicular germ cell tumor, melanoma, and cholangiocarcinoma, indicating that the scope of WNT6 function is broader." (PMID 33425886, 2020). "Interestingly, WNT6 and HOXA9 were also found to be co‐expressed in other cancer types, including leukemia, testicular germ cell tumor, melanoma, and CHOL." (PMID 31923345, 2020).
basal cell carcinoma (3 papers, 2020 to 2022). A carcinoma involving the basal cells. "KEGG analysis also highlights several pathways associated with disease including “basal cell carcinoma” (Wnt6, Gli2, Wnt10a) and “htlv-i infection” (Smad4, Wnt10a, Prkacb, Wnt6, Tgfbr2) in M. spretus." (PMID 34794440, 2021). "Among the DEGs in PA, we identified enrichment in cancer pathways (e.g., basal cell carcinoma) among the most relevant KEGG pathways, and significant downregulation of growth-related genes such as Wnt6 (Wnt Family Member 6, FC = −2.019, p = 4.18E-05) and FZD5 (frizzled-5, FC = −1.493, p = 0.0001)." (PMID 36046021, 2022).
hepatocellular carcinoma (3 papers, 2018 to 2023). A malignant tumor that arises from hepatocytes. "The combination of WNT6 expression with the expression of hypoxia pathway proteins identified a subgroup of hepatocellular carcinoma patients predictive of poor survival." (PMID 30257451, 2018).
leukemia (3 papers, 2020 to 2022). A malignant (clonal) hematologic disorder, involving hematopoietic stem cells and characterized by the presence of primitive or atypical myeloid or lymphoid cells in the bone marrow and the blood. "We identified differential methylation of genes that have been related to cancers such as lymphoma (WNT6, TP73, and CD37), leukaemia (MEIS1, HOXA4, and HOXA5) or neuroblastoma (TP73), as well as genes related to cardiovascular diseases (UCN, PRDM16, TCAP, ALOX5)." (PMID 35354948, 2022).
lung tuberculosis (3 papers, 2016 to 2023). "This review focuses on the regulation of Wnt5a, Wnt3a, and the recently identified Wnt6 and their functional role in bacterial infections with a primary focus on pulmonary tuberculosis, a leading infectious cause of morbidity and mortality worldwide." (PMID 28082976, 2016). "Importantly, WNT ligand WNT6 has been implicated in foam cell formation during pulmonary TB." (PMID 37871034, 2023). "Aberrant WNT6 signaling is related to various pathologies, such as promoting cancer development, lung tuberculosis, and kidney fibrosis and improving the symptoms of Rett syndrome (RTT)." (PMID 33425886, 2020).